RN7SL81P (RNA, 7SL, cytoplasmic 81, pseudogene)
Gene: Miscellaneous RNA gene on chromosome 7 (128,761,338 to 128,761,598, forward strand). Ensembl gene ENSG00000244218.
Homologues: Orthologues: chimpanzee Metazoa_SRP (93% identical), macaque Metazoa_SRP (81% identical), dog Metazoa_SRP (53% identical). Paralogues in human: RN7SL1 (85% identical), RN7SL2 (85% identical), RN7SL3 (84% identical), RN7SL664P (84% identical), RN7SL426P (83% identical), RN7SL126P (82% identical), RN7SL679P (82% identical), RN7SL14P (81% identical), RN7SL296P (81% identical), RN7SL408P (81% identical), RN7SL712P (81% identical), RN7SL118P (81% identical), and 704 more.